TRIM40 (tripartite motif containing 40)
Description:
E3 ubiquitin-protein ligase that plays a role in the limitation of the innate immune response. Mediates inhibition of the RLR signaling pathway by ubiquitinating RIGI and IFIH1 receptors, leading to their proteasomal degradation. Also promotes the neddylation of IKBKG/NEMO, stabilizing NFKBIA, and thereby inhibiting of NF-kappa-B nuclear translocation and activation.
Synonyms: RNF35
Tractability: No criterion of Open Targets' tractability assessment is met for any kind of drug.
Gene: Protein-coding gene on chromosome 6 (30,136,028 to 30,151,592, forward strand). Ensembl gene ENSG00000204614.
Subcellular location (Human Protein Atlas): Cytosol
Gene Ontology:
Molecular function: protein binding; ubiquitin protein ligase activity; metal ion binding; zinc ion binding
Biological process: negative regulation of canonical NF-kappaB signal transduction; negative regulation of protein catabolic process; negative regulation of protein localization to nucleus; protein neddylation; innate immune response; negative regulation of non-canonical NF-kappaB signal transduction
Cellular component: IkappaB kinase complex; cytoplasm
Genetic constraint (gnomAD): Loss-of-function variants: 28 observed, 28.03 expected, observed/expected ratio (o/e) 1, 90% interval 0.74 to 1.37. The upper end of that interval is the gene's LOEUF score, 1.37, which puts it in group 5 of 6, group 1 being the genes least tolerant of losing a copy. Missense variants: 289 observed, 322.78 expected, observed/expected ratio (o/e) 0.9, 90% interval 0.81 to 0.99. Synonymous variants: 114 observed, 127.19 expected, observed/expected ratio (o/e) 0.9, 90% interval 0.77 to 1.05.
Homologues: Orthologues: chimpanzee TRIM40 (99% identical), macaque TRIM40 (94% identical), pig TRIM40 (67% identical), rabbit TRIM40 (63% identical), mouse Trim40 (61% identical), rat Trim40 (61% identical). Paralogues in human: TRIM6 (28% identical), TRIM60 (26% identical), TRIM5 (26% identical), TRIM43B (26% identical), TRIM64C (26% identical), TRIM43 (25% identical), TRIM75 (25% identical), TRIM21 (24% identical), TRIM22 (24% identical), TRIM64 (24% identical), TRIM64B (24% identical), TRIM68 (24% identical), and 68 more.
Diseases named in the same sentence as TRIM40 in open-access papers:
TRIM40 is named in the same sentence as 21 diseases in open-access papers, as found by Europe PMC text mining. Sharing a sentence is not in itself a finding about the gene and the disease. The quoted sentences say what the papers report.
inflammatory bowel disease (5 papers, 2023 to 2025). A spectrum of small and large bowel inflammatory diseases of unknown etiology. "TRIM40 is a pathogenic driver of inflammatory bowel disease through subverting intestinal barrier integrity." (PMID 40034711, 2025). "From the DMR analysis, TRIM40 has recently been associated with inflammation in the context of inflammatory bowel disease, RNF14 regulates mitochondrial and immune-related functioning, and HIVEP3 regulates the development of innate-like T cells." (PMID 38296944, 2024). "Similarly, inappropriate expression of epigenetically silenced TRIM40 in the colonic epithelium has been linked to inflammatory bowel disease." (PMID 41168352, 2025). "A previous study showed that the upregulated TRIM40 could promote the progression of inflammatory bowel disease." (PMID 40034711, 2025). "TRIM40 may serve as a therapeutic target to limit the onset and progression of inflammatory bowel disease (IBD)." (PMID 40564099, 2025).
gastrointestinal carcinomas (2 papers, 2018 to 2021). "Interestingly, NEDDylation of NEMO by the RING E3 ligase TRIM40 in the gastrointestinal tract inhibits NF-kB activity and TRIM40 is down regulated in gastrointestinal carcinomas." (PMID 34631557, 2021).
viral infections (2 papers, 2022 to 2023). "Bats may have evolved to express TRIM40 in response to viral infections to control immunopathogenesis." (PMID 38005825, 2023).
autoimmune disease (1 paper, 2021). A disorder resulting from loss of function or tissue destruction of an organ or multiple organs, arising from humoral or cellular immune responses of the individual to their own tissue constituents. "For example, one of TRIM40 SNPs, rs757262, can balance the risk of developing different autoimmune diseases." (PMID 34177938, 2021).
cardiac hypertrophy (1 paper, 2026). "TRIM40 deficiency attenuated cardiac hypertrophy and dysfunction, whereas its overexpression exacerbated pathological remodeling." (PMID 41572508, 2026). "This study investigates the role of the E3 ubiquitin ligase Tripartite Motif-Containing 40 (TRIM40) in cardiac hypertrophy." (PMID 41572508, 2026).
cognitive decline (1 paper, 2025). "Further analysis in prodromal cases revealed that subjects with TRIM40 heterozygous alleles (C/T) alleles experienced faster motor and cognitive decline, while those with IP6K2 homozygous G alleles showed greater depression over 12 years in prodromal cases." (PMID 40542411, 2025).
colitis (1 paper, 2023). Inflammation of the colon. "Accordingly, Trim40-deficient male mice are highly resistant to dextran sulfate sodium (DSS)-induced colitis." (PMID 36755029, 2023). "Here the authors report that TRIM40, an E3 ligase, disrupts cortical actin formation and leads to loss of epithelial barrier integrity, and that genetic loss of TRIM40 is protective against experimental colitis in male mice." (PMID 36755029, 2023). "To test this hypothesis, we generated Trim40-deficient (Trim40−/−) mice and examined the pathological effects of Trim40 loss on murine colitis." (PMID 36755029, 2023). "Notably, our results highlighted the resistance to DSS-induced colitis in Trim40-deficient mice, supporting the idea that DSS itself is not an essential process of IBD onset." (PMID 36755029, 2023).
COVID-19 (1 paper, 2023). A disease caused by infection with severe acute respiratory syndrome coronavirus 2. "TRIM40′s associations with kidney disease and regulatory functions in immunity both align with a role in resistant hypertension and COVID-19, respectively." (PMID 37759668, 2023).
cancer (3 papers, 2017 to 2021). A tumor composed of atypical neoplastic, often pleomorphic cells that invade other tissues. "TRIM40 has been reported to inhibit nuclear factor-kappaB (NF-κB) activity and prevent inflammation from causing cancer in the gastrointestinal tract." (PMID 33493136, 2021). "Genes characteristic of cancer cells – Oit3, Tnxb, Zfr2, VpreB3, Trim40." (PMID 28031533, 2017).
tumor (3 papers, 2018 to 2023). "Based on our findings, as TRIM40 is involved in the regulation of actin dynamics, its upregulated expression in certain tumor cells or stages may contribute to tumor metastasis." (PMID 36755029, 2023). "In contrast, a few members including TRIM8, TRIM15, TRIM24, and TRIM40 are characteristically downregulated in CRC and exert tumor-suppressive activities." (PMID 33066016, 2020).
infection (2 papers, 2023 to 2025). The state of being infected such as from the introduction of a foreign agent such as serum, vaccine, antigenic substance or organism. "We next analyzed the role of TRIM40 in the context of infection." (PMID 38005825, 2023). "In Pteropus vampyrus, but not human cells, NiV induces TRIM40 expression within 16 h after infection, and knockdown of TRIM40 correlates with reduced NiV titers as compared to control cells." (PMID 38005825, 2023). "We then measured TRIM40 gene expression in these cells and observed a dose-dependent induction of TRIM40 expression in PVK4, but not A549, cells within 16 h of infection." (PMID 38005825, 2023).
kidney disease (1 paper, 2023). "TRIM40 also has associations with IgA nephropathology, which causes kidney disease; it is thought to suppress IgA1-induced GMC proliferation by inhibiting the activation of NLRP3 inflammasome." (PMID 37759668, 2023).
TRIM40 also shares sentences with these, for which no sentence is quoted: agranulocytosis (1 paper); depression (1); glomerulonephritis (1); heart failure (1); IgA nephropathy (1); lung adenocarcinoma (1); resistant hypertension (1); schizophrenia (1); type 1 diabetes (1).